LINC01738 (long independently transcribed non-coding RNA 1738)
Gene: Long non-coding RNA gene on chromosome 1 (47,687,725 to 47,704,029, forward strand). Ensembl gene ENSG00000227947.
Diseases named in the same sentence as LINC01738 in open-access papers:
LINC01738 is named in the same sentence as 1 disease in open-access papers, as found by Europe PMC text mining. Sharing a sentence is not in itself a finding about the gene and the disease.
LINC01738 shares sentences with these, for which no sentence is quoted: tumor (1 paper).